MTOR (mechanistic target of rapamycin kinase)
Diseases named in the same sentence as MTOR in open-access papers (continued):
Sharing a sentence is not in itself a finding about the gene and the disease.
tumor (continued). "Among the recipients of renal transplantation in Taiwan, mTOR inhibitors with exposure more than 5 years provided a protective role in reducing the risk of overall neoplasm and urothelial malignancy." (PMID 30117312, 2018). "For example, Fbxw7 targets mTOR, c-Myc, c-Jun, cyclin E, and several other proteins implicated in oncogenesis, thus functioning as a tumor suppressor." (PMID 30359271, 2018). "The PI3K/AKT/mTOR signaling pathway is associated with tumor growth, survival, metastasis, and treatment-resistant in OSCC." (PMID 30115834, 2018). "The role of mTOR pathway in tumor angiogenesis has been documented and associated to the activity of mTORC1 complex." (PMID 29755672, 2018). "Because of both their limited effects on tumor growth and the systemic effects on the immune system linked to the chronicity of treatments performed using mTOR inhibitors, research for the identification of new therapeutic strategies is moving forward." (PMID 29772672, 2018). "LKB1 is recognized as a tumor suppressor that associates bioenergetics with cell growth control and downregulation of mTOR activity through AMPK activation." (PMID 29629339, 2018). "Loss of TSC1, TSC2, or PTEN leads to hyperactivation of mTOR and therefore the cells and tissues deficient of these tumor suppressors are widely used in the study of mTOR signaling." (PMID 29362480, 2018). "On the contrary, the non-tumor immortalized MCF-10A cells appeared to be more susceptible to the effects of mTOR/LDH-A activation and underwent a metabolic reprogramming resulting in the manifestation of increased self-renewal and clonogenic potential." (PMID 30138330, 2018). "Activation of mTOR is associated with malignant tumor progression, resistance to chemotherapy and molecularly targeted therapies, and dismal prognosis." (PMID 28126011, 2017). "Two key tumor-associated proteins p21 and mTOR were shown to be down-regulated after omeprazole treatment." (PMID 29050283, 2017). "Further, p-mTOR overexpression was associated with patient age, tumor location, depth of invasion (OR = 1.63, 95%CI 1.08–2.45, P = 0.02) and TNM stage (OR = 1.73, 95%CI 1.29–2.32, P < 0.001)." (PMID 29233126, 2017). "Tumor inhibition was associated with reduced expression of autophagy negative regulator mechanistic target of rapamycin (mTOR) and decreased trend of serum pro-inflammatory cytokines." (PMID 29262645, 2017). "In the hypermutated HGG11 tumor pair, the primary tumor harbored a missense MTOR mutation, while at recurrence the tumor acquired a PI3K catalytic subunit PIK3CD passenger mutation." (PMID 29084603, 2017). "Similar analysis following tumor progression demonstrated mTOR mutations that render mTORC1 resistant to rapalogs." (PMID 29104248, 2017). "The importance of the mTOR pathway in GEP-NET is further underlined by the significant anti-tumor effects shown by the mTOR inhibitor everolimus, now used in the treatment of advanced NET." (PMID 28423496, 2017). "Improved prognosis associated with elevated mTOR in NEAT suggests that tumours dependent upon mTOR have enhanced sensitivity to sunitinib." (PMID 28648142, 2017). "The signaling pathway, Akt/PI3K/PTEN/mTOR, was related to the pathogenic process of several neoplastic diseases, and the activation of this signaling pathway was also associated with poor survival in solid tumors." (PMID 28938690, 2017). "We have demonstrated that dual inhibition of PI3K and mTOR is associated with strong anti-tumor activity in LMS, which was significantly higher than that of either mTOR inhibition (everolimus) or PI3K inhibition (BKM120) alone." (PMID 28002802, 2017). "Intriguingly, ADAMTS9 inhibits tumor growth by blocking the mTOR pathway, which has long been known to be associated with aging." (PMID 28244876, 2017). "Of the different signaling cascades affected by TGF-β, inhibition of the mammalian target of rapamycin (mTOR) pathway has been directly implicated in suppressing anti-tumour efficacy of NK cells." (PMID 28817109, 2017).
tumor (continued). "Although currently published (pre-)clinical data report contradictory results, KRAS and PIK3CA mutation status have previously been associated with respectively resistance and sensitivity to mTOR inhibition in particular tumor types." (PMID 28903445, 2017). "The aims of this targeted next generation sequencing (NGS) study were to assess tumor cytology genotype diversity, to survey for potential adverse prognostic biomarkers and the prevalence of mTOR pathway variants." (PMID 29212165, 2017). "mTOR inhibitors have been widely used in LT recipients, not only for reducing the risk of allograft rejection and neoplasm, but also for renal protection." (PMID 28427351, 2017). "Existing evidences have reported mammalian target of rapamycin (mTOR) over-expression and/or hyper-activation in RCCs, which is associated with tumor progression." (PMID 28257457, 2017). "Aberrant activation of mTOR pathway either by loss of tumor suppressors or activation of oncogenes promotes tumor growth, which has been shown in many malignant cell lines." (PMID 28178668, 2017). "Folliculin is thought to function as a tumor suppressor that is associated with the mammalian target of rapamycin (mTOR) pathway." (PMID 28151982, 2017). "Previous studies have reported that dysregulation of mTOR signaling pathway is associated with tumorigenesis, tumor angiogenesis, metastasis, and anticancer drug resistance." (PMID 28811537, 2017). "Although tumor genetic screenings identified mTOR and TSC mutations that are associated with long term therapeutic benefits, most tumors eventually relapse within one or two years." (PMID 28280521, 2017). "In line with previous findings suggesting that mTOR mutations occur predominantly at advanced stages of tumor evolution in subclonal metastatic populations, the metastasis revealed a private mTOR mutation." (PMID 29088767, 2017). "Our group pioneered the use of rapamycin as a single agent to treat HNSCC xenografts; rapamycin rapidly decreased mTOR activity, as indicated by its marker, pS6, and caused rapid tumor regression." (PMID 28822012, 2017). "mTOR inhibitors (rapamycin and everolimus) effectively decreased mTOR activity in vivo and caused a remarkable decrease in tumor burden (P < 0.001)." (PMID 28595616, 2017). "Angiogenesis is also a crucial step in tumor formation and progression, and several recent studies support the notion that inhibition of mTOR is associated with decreased VEGF expression." (PMID 29108276, 2017). "For example, two distinct and spatially separate mutations in TSC1 and MTOR, along the PI3 K/AKT/mTOR pathway, that activate mTOR kinase through different mechanisms were detected in different regions of the same tumor." (PMID 27766604, 2016). "mTOR-deficiency in myeloid cells causes a significantly accelerated rejections of alloskin and tumor grafts in mice, due to the decreased cell number and the defect immunosuppressive ability of CD11b+ Ly6Chigh M-MDSCs." (PMID 26833095, 2016). "Aberrant activation of mTOR pathway induced by the loss of tumor suppressors and oncogene stimulation can significantly promote tumor growth, angiogenesis and metastasis." (PMID 27835987, 2016). "Positive expression of mTOR and p-mTOR was significantly associated with the unfavorable conditions on the depth of tumor invasion, TNM stage, differentiation degree and lymph node metastasis." (PMID 27835987, 2016). "mTOR inhibition sensitises PTEN-deficient tumours to trastuzumab, thereby suggesting that the combination of everolimus, the mTOR inhibitor, and trastuzumab have a role in the treatment of HER2-overexpressing BC." (PMID 27357210, 2016). "Loss-of-function mutations in the NF1 tumor suppressor gene affects mTOR pathway, leading to constitutive activation of mTOR." (PMID 26859683, 2016).
tumor (continued). "Most strikingly, 3 days after transgene induction mTOR/S6 signaling was activated strictly in GLI2A-expressing nascent tumor cells at the base of gastric glands, establishing a tight association between the Hh/Gli2 and mTOR pathways during tumor initiation." (PMID 26859571, 2016). "Altogether, our integrated analysis demonstrated that 13 of the 16 uRCC tumours with MTOR, TSC1, TSC2 or PTEN mutations exhibited hyperactive mTORC1 signals." (PMID 27713405, 2016). "In this study, the authors starting from a synthetic lethal screen, demonstrate that tumor cells with mutations in ATM exhibit increased sensitivity to MEK1/2 inhibition through the modulation of the AKT/mTOR pathway." (PMID 27922010, 2016). "In the present study, we find that RPM or mTOR deletion causes the deficiency of immunosuppressive CD11b+ Ly6Chigh M-MDSCs in transplant and tumor-bearing mouse models." (PMID 26833095, 2016). "The activation of the PI3K/Akt/mTOR pathway is associated with tumour growth 27, 28, whereas the inactivation of Akt and mTOR suppresses tumour growth." (PMID 26800397, 2016). "Our results found that everolimus, via mTOR suppression, effectively reduced gut microbiome-associated metabolites in both obese and lean tumor tissues." (PMID 26959121, 2016). "Sirolimus has been described to decrease tumor burden by suppressing mTOR (Mammalian target of rapamycin) signaling pathway and causing cell apoptosis." (PMID 27829366, 2016). "It is believed that deregulation of mTORC1 signaling in tumors is due to either loss of function of upstream tumor suppressor proteins or activating mutations within oncogenes that upregulate mTOR pathway." (PMID 27409169, 2016). "The p-mTOR overexpression was strongly associated with depth of invasion (OR = 1.63, 95%CI: 1.08–2.45, P = 0.02), and tumor stage (OR = 1.73, 95%CI: 1.29–2.32, P < 0.001)." (PMID 28005970, 2016). "The PKC, MAPK and PI3K/AKT/mTOR signaling cascades have been shown to be associated with tumor growth." (PMID 26988753, 2016). "We also investigated phosphorylation of the Akt1 protein as an indicator of the Akt1/mTOR pathway activation in 43 tumor samples in association with ZNF703 expression." (PMID 27650486, 2016). "For instance, the loss of function of PTEN or activation of PI3K/AKT/mTOR signaling can enhance the expression of CD274 in tumor cells, which further leads to the escape from the surveillance by the immune system." (PMID 27855694, 2016). "The PI3-KAkt/mTOR pathway plays a central role in regulating protein synthesis and cell proliferation, and is associated with tumorigenesis, angiogenesis, tumor growth, and metastasis." (PMID 27285995, 2016). "The mTOR signaling and downstream effector pathways are well described as implicated in oncogenesis, tumor progression, metastasis, and therapy resistance." (PMID 27015118, 2016). "PTEN is a tumor suppressor gene which negatively regulates the PI3K/Akt/mTOR pathway, and loss of PTEN was previously identified as a poor prognostic marker." (PMID 27121209, 2016). "A major priority in developing new generation mTOR-targeted therapy is to elucidate molecular mechanism of mTOR complexes and to identify tumor subtype and underlying response biomarker that will help treatment stratification." (PMID 27563814, 2016). "Recently, we reported that IL-24 effectively suppressed AKT/mTOR signaling and its associated tumor cell migration." (PMID 27602961, 2016). "Positive expression of mTOR/p-mTOR was found to be significantly associated with the worse conditions on tumor invasion, differentiation degree, TNM stage and LNM, all of which were critical factors resulting in the negative prognosis of ESCC." (PMID 27835987, 2016). "The tumor growth inhibition is simultaneous associated with the diminution of mTOR and Hh pathways, which are implicated in the pathogenesis of RMS." (PMID 26420980, 2015). "The previous study had proved that the anti-tumor effect of cardamonin was associated with mTOR inhibition." (PMID 25996501, 2015).
tumor (continued). "Differences in the activities of several other signaling molecules, including mTOR and Sirtuins, have also been implicated in the differential effects of CR on normal versus tumor cells." (PMID 25855056, 2015). "To investigate the mechanism underlying mLST8-mediated promotion of tumor growth, we assessed the effects of mLST8-KD on the formation of mTOR complexes and the activity of downstream signaling components in HCT116 and LNCaP cells." (PMID 25906254, 2015). "One report has found that in an embryonal tumor cell line miR-let-7 is linked to mTOR signaling and the miRNA remains underexpressed and it is upregulated in LIN28 knockdown cells along with IGF/PI3K/mTOR pathway signaling silencing." (PMID 25652781, 2015). "This overactive RAS signalling leads to increased activity of downstream effectors, most notably the RAS/RAF/ERK and PI3K/AKT/mTOR signalling pathways linked to increased cell proliferation and tumour formation." (PMID 25883647, 2015). "Here, we observed the role of the mTOR pathway in autophagy pathway, because some studies indicated that inhibition of the Akt-mTOR pathway was consistently associated with triggering autophagy in tumor cells." (PMID 26311737, 2015). "The authors also reported these effects can be reduced by RAPA and suggested the involvement of the stromal mTOR pathway on blood vessel formation and tumor growth in Caveolin-1–deficient tumors." (PMID 26098779, 2015). "Liu et.al revealed temporal mTOR inhibition protected Fbxw7-deficient mice from radiation-induced tumor development." (PMID 25749036, 2015). "Crucial tumor associated pathways such as Notch, wnt, mTOR are modulated by V-ATPase through endosomal trafficking and pH maintenance." (PMID 25686833, 2015). "The allosteric AKT inhibitor, MK-2206, and γ-tocotrienol can down-regulate AKT/mTOR signaling activity, then induce cell cycle arrest in the G0/G1 phase of the cell cycle, cause apoptosis and reduce tumor growth." (PMID 24970807, 2014). "Dramatic tumor shrinkage was noted in a recent mutated KRAS lung cancer model when treated with a combination of a dual PI3K/mTOR inhibitor and a MEK (MAP/ERK kinase) inhibitor." (PMID 24624093, 2014). "PTEN encodes a phosphatase that functions as a tumor suppressor by negatively regulating the PI3K/Akt/mTOR pathway." (PMID 25126591, 2014). "In an analysis of tumor from 195 patients with NETs arising in various sites, primarily small intestine, expression of mTOR or its activated downstream target p-EIF4EBP1 was associated with a higher proliferative index." (PMID 25092520, 2014). "This suggests that activation of mTOR in this tumor cohort is associated with an intact estrogen (ligand) dependent signaling pathway." (PMID 24887419, 2014). "In tumors three and four, there was a distinct somatic mutation in MTOR (categories 2 and 3, respectively) in each tumor, and PBRM1 and KDM6A and NRAS mutations (all category 3) in tumor three." (PMID 25159823, 2014). "The phosphatidylinositol 3-kinase (PI3K)/mammalian target of rapamycin (mTOR)/AKT pathway has been linked to the pathophysiology of several neoplastic diseases." (PMID 24777052, 2014). "Enhanced activation of phosphatidyl-inositol-3-kinase (PI3K)-mTOR signaling, which is commonly observed in tumors, stimulates the translation of various tumor-associated factors with highly structured 5′UTRs such as cyclin D1." (PMID 24416388, 2014). "High-mobility group box 1 (HMGB1) activates the FAK/PI3K/mTOR signaling cascade and regulates tumor-associated cell migration through the interaction with BTB domain." (PMID 24524196, 2014). "Its prevention on HNSCC tumor development has been reported to be through mTOR inhibition by causing cell cycle arrest and inhibiting protein translation." (PMID 24457597, 2014). "The two tumors in the left kidney harbored distinct point mutations in the MTOR gene (tumor three, p.L2427P; tumor four, p.T1652A)." (PMID 25159823, 2014).
tumor (continued). "Taken together, metformin suppresses EC cell growth in vitro and in vivo due to its ability to reduce the CSCs population as well as causing inhibition of the mTOR pathway in bulk tumor cells." (PMID 24859412, 2014). "The enhanced tumor growth in the leucine-supplemented control group cannot be explained by changes in mTOR signaling in the tumor, but was associated with greater glucose availability (reduced fasting insulin levels and diminished glucose clearance)." (PMID 24685128, 2014). "Firstly, positive pT3/pT4 tumours were associated with a worse prognosis, which is in accordance with previous data that have reported upregulation of the mTOR pathway as an important prognostic factor." (PMID 25202348, 2014). "In the group of pT3/pT4 tumours, p-mTOR expression was associated with a worse survival rate, although the differences were only significant for 5-year DFS." (PMID 25202348, 2014). "Loss of TSC2 leads to activation of MTOR and downstream signaling elements, causes endoplasmic reticulum (ER) stress, activates the unfolded protein response, and results in tumor development." (PMID 25469175, 2014). "As predicted, the most frequently mutated genes in gynaecological cancers are genes of the pAKT/mTOR pathway, but within this pathway, the mutational frequencies vary between tumour types." (PMID 24671188, 2014). "The aberrant activation of mTOR pathway either by loss of tumor suppressors or activation of oncogenes promotes tumor growth in various malignant cell lines." (PMID 25505994, 2014). "Simultaneous inhibition of BTK and mTOR causes apoptosis both in vitro and in vivo and results in tumor regression in a xenograft model." (PMID 24970801, 2014). "Either of these mutations results in constitutive mTOR expression and impaired tumor suppression in multiple tissues." (PMID 24612911, 2014). "The synergistic anti-tumor effects were associated with a more sustained inhibition of PI3K/Akt/mTOR signaling activity and down-stream regulators of cell growth, including myc, cyclin D, and retinoblastoma (RB) protein." (PMID 24387108, 2014). "mTOR activation is implicated in almost every tumor type and the process of aging; both of which are slowed by CR, suggesting it to be the central molecule modulated during CR." (PMID 25026276, 2014). "Our data showed that deficiency in tuberin and activation of mTOR resulted in upregulation of YY1 in tumor kidney tissue of TSC patients." (PMID 23705901, 2013). "In mice that received fractionated radiation alone, tumors grew slowly during the early two weeks, then the growth rate resumed similar to the control group (P > 0.05), meanwhile in association with high level of p-mTOR in tumor tissues." (PMID 23886294, 2013). "The activation of AKT through phosphorylation is known to activate mTOR (mammalian target of rapamycin), which regulates a variety of functions associated with tumor pathogenesis." (PMID 23555046, 2013). "Deficiency in tuberin and increased mTOR activity result in increased the protein expression of YY1 in tumor kidney tissue of patients with TSC." (PMID 23705901, 2013). "Immunosuppression through mTOR inhibition can improve the prospects due to the regression of tumours and their associated complications." (PMID 23401839, 2013). "The study has also revealed differences of MBC to FBC and between sporadic and familial MBC which are of importance in optimising treatment strategies and underlying relevance of the PIK3CA/mTOR pathway in tumour biology." (PMID 23971979, 2013). "Loss of PTEN, which is a tumor-suppressor gene that inhibits the PI3K/AKT/mTOR pathway, causes the aberrant mTOR pathway activation." (PMID 23468988, 2013). "On subgroup analysis, a non-statistically significant increase in the risk of FAEs was found according to different mTOR inhibitors, tumor types or controlled therapy." (PMID 23785409, 2013).